TIMP3 (TIMP metallopeptidase inhibitor 3)
Diseases named in the same sentence as TIMP3 in open-access papers (continued):
Sharing a sentence is not in itself a finding about the gene and the disease.
Insulin resistance (14 papers, 2011 to 2025). Increased resistance towards insulin, that is, diminished effectiveness of insulin in reducing blood glucose levels. "In the muscle, TACE/TIMP3 deregulation associates with insulin resistance, and in the liver with NASH development." (PMID 22359625, 2012). "It has emerged that TIMP-3 can affect gut microbiota and, subsequently, obesity and insulin resistance." (PMID 35207132, 2022). "Mice deficient in TIMP-3 demonstrate elevated levels of TNF-α and develop insulin resistance and hepatic steatosis, mediated by increased TACE activity." (PMID 21980496, 2011). "Differential display experiments on mRNA extracted from the muscle of insulin receptor haplo-insufficient mice (Insr+/−) with or without insulin resistance mice identified a marked decrease in TIMP3 expression in Insr+/− mice with insulin resistance compared to insulin sensitive animals." (PMID 37445827, 2023). "In STZ-induced T2D rats, miR-21 antagomir could improve insulin resistance and lipid metabolism disorder by upregulating the expression level of metalloproteinases 3 (Timp3)." (PMID 36286043, 2022). "Similarly, in a mouse model, overexpression of TIMP-3 in macrophages protects from metabolic inflammation and related metabolic disorders such as insulin resistance, glucose intolerance and non-alcoholic steatohepatitis." (PMID 35082694, 2021). "Pathways and mechanisms linking the TACE/TIMP-3 dyad to insulin resistance and hepatic steatosis may involve expression of proteins playing a role in fatty acid uptake, triglyceride synthesis and methionine metabolism." (PMID 21980496, 2011). "The miR-21 antagomir increases the expression level of tissue inhibitor of metalloproteinases 3 (TIMP3), thereby improving insulin resistance and disordered lipid metabolism in STZ-induced T2DM rats." (PMID 40941416, 2025). "Ablation of TIMP-3 in mouse enhanced inflammation by dysregulating the activity of ADAM17 (a TIMP-3 target metalloproteinase) and the subsequent release of its substrate TNF, thus promoting insulin resistance and hepatosteatosis." (PMID 33673623, 2021). "Furthermore, ablation of TIMP-3 and subsequent dysregulated ADAM17 activity and TNF release promoted insulin resistance and hepatosteatosis." (PMID 33579029, 2021). "The TACE/TIMP-3 system has recently emerged as a novel mediator between metabolic stimuli and innate immunity; however, the effects of pharmacologic TACE-inhibition on insulin resistance and hepatic steatosis remain to be established." (PMID 21980496, 2011).
meningioma (12 papers, 2015 to 2026). A generally slow growing tumor attached to the dura mater. "As mentioned, loss of H3K27me3 modifications has been associated with meningioma recurrence in retrospective clinical studies, and hypermethylation of TIMP3, CDKN2A, and TP73 has been correlated with meningioma grade." (PMID 38001599, 2023). "In the case of hypermethylation of TIMP3, studies have shown that this methylation event inhibits matrix metalloproteinases and has been associated more aggressive and higher grade meningiomas." (PMID 33194703, 2020). "The promoter hypermethylation of TIMP3 was associated with a more aggressive and higher-grade meningioma phenotype and poor prognosis." (PMID 33014773, 2020). "For instance, TIMP3 inactivation as a result of gene promoter methylation appears to be involved in meningioma progression as it is associated with more aggressive, high-grade meningioma phenotype." (PMID 25648363, 2015). "The TIMP3 gene is located on chromosome 22q12; interestingly, the majority of meningiomas had deletions in this chromosome region, which also contained the NF2 tumor suppressor gene." (PMID 30279357, 2018). "Similar to TIMP3, repression of HOXA7, HOXA9, and HOXA10 in meningioma is also associated with clinically aggressive behaviour." (PMID 26101774, 2015). "Hypermethylation of TIMP3 is present in 67% of anaplastic meningiomas, but only in 22% of atypical and 17% of benign meningiomas." (PMID 26101774, 2015). "There is a growing body of evidence indicating that TIMP3 methylation could be an epigenetic marker of meningioma progression." (PMID 33014773, 2020). "Another candidate engaged in meningioma progression is the TIMP3 (the tissue inhibitor of metalloproteinase 3) gene on 22q12, because it has been shown that anaplastic meningiomas showed much higher hypermethylation of its promoter than atypical and benign cases." (PMID 27429002, 2016). "Thus, inactivation of TIMP3 by methylation may be involved in meningioma progression and can be a potential marker of an aggressive, high-grade meningioma phenotype." (PMID 26101774, 2015). "Hsa-miR-21-5p enhanced proliferation and viability of KT21-MG1 meningioma cells and showed a regulatory effect on IL6R, IL6ST and other predicted target genes TIMP3, PIK3R, RHOB, and SASH1 by interacting with 3'UTRs." (PMID 42196381, 2026). "In contrast to NF2, the promoter methylation of tissue inhibitor of metalloproteinase 3 (TIMP3), located quite close to the NF2 gene, is inactivated in meningiomas." (PMID 26101774, 2015). "In addition, hypermethylation of TIMP3, Cyclin-Dependent Kinase Inhibitor 2A (CDKN2A), and TP73 has been correlated with meningioma grade." (PMID 38001599, 2023). "It is important to divide these genes into several groups according to their function on the progression of meningiomas; benign tumors which harbor TP73/RASSF1A hypermethylation, for example, are more likely to turn malignant while the hypermethylation of TIMP3 marks a shorter time to recurrence." (PMID 33014773, 2020). "Although RF predicts TIMP3, INMT and SLC16A1 followed by ALPL as the important feature genes in subtype 3, the expressions of these three genes are not consistently lower or higher than all other subtypes of meningioma, which restricts their potent of being biomarkers for meningioma." (PMID 33807688, 2021).
thyroid cancer (12 papers, 2012 to 2025). "The methylation of TIMP3 has commonly been found in thyroid cancer tissues and associated with extrathyroidal invasion and lymph node metastasis." (PMID 38542164, 2024). "TIMP3 promoter methylation is observed in many tumors such as esophageal, gastric, and thyroid cancer, and causes loss of TIMP3 protein expression." (PMID 27410681, 2016). "According to TCGA data, the TIMP3 expression level is lower in thyroid cancer tissues than in normal tissues and is correlated with the OS of thyroid cancer patients." (PMID 38542164, 2024). "Based on Anania and Baldini’s results, different cell lines show various TIMP3 mRNA levels, although these cell lines have the same histology of thyroid carcinomas." (PMID 38542164, 2024). "Our previous findings clearly demonstrated a negative regulatory role of TIMP3 in thyroid cancer; however, the downstream effectors of TIMP3 in thyroid tumor cells are not known." (PMID 36503426, 2022). "Overall, this study provides a broader view on the onco-suppressive role of TIMP3 in thyroid cancer, useful for the design of therapeutic approaches based on TIMP3 restoration." (PMID 36503426, 2022). "TIMP3 reduces thyroid cancer cell proliferation, migration, and invasion of thyroid cancer." (PMID 38542164, 2024). "Promoter methylation status of genes with reported associations in thyroid cancer (CASP8, CDKN2A, DAPK1, ESR1, NIS, RASSF1 and TIMP3) were examined in a cohort of follicular thyroid cancers comprising of 26 Hurthle and 27 Classic subtypes utilizing quantitative methylation-specific PCR." (PMID 27158284, 2015). "Among the selected genes in the 22q area, CHEK2, LIMK2, and TIMP3 have already been reported to be deleted/down-regulated in thyroid cancer; the 22q deletion may play a role in thyroid carcinogenesis." (PMID 22558328, 2012). "Furthermore, as reported in other tumor types, recent evidences suggest that TIMP3 suppression in thyroid cancer may be related also to miRNA deregulation." (PMID 36503426, 2022). "First, we verified the expression of 9 immune-related prognostic factors, AKAP12, APOC1, TIMP3, ADAMTS9, ANK2, HTRA3, SYNDIG1, ​​ADAMTS5 and DACT1, in 11 thyroid cancer cell lines in the CCLE database." (PMID 36591507, 2022). "The difference in TIMP3 expression after PROX1 silencing in CGTH-W-1 and FTC-133 is probably a result of opposing regulation and variable baseline expression of MMPs and their inhibitors in cell lines derived from thyroid carcinomas." (PMID 31717665, 2019).
glioblastoma (11 papers, 2012 to 2025). The most malignant astrocytic tumor (WHO grade IV). "In glioblastoma, elevated TIMP3 expression is associated with improved patient survival and enhanced infiltration of immune cells." (PMID 41009435, 2025). "TIMP-3 is frequently found in meningiomas, glioblastomas, pancreatic endocrine carcinomas, and cervical or lung cancers." (PMID 29467412, 2018). "Moreover, hypermethylation of the TIMP3 promoter has been identified as a common reason of decreased TIMP3 expression levels in numerous tumors like secondary glioblastomas, kidney cancer, or pancreatic adenocarcinomas." (PMID 24722350, 2014). "Hsa_circ_0001445 could regulate VEGFA mRNA through binding to SRSF1 in glioblastoma, while in HCC, it sponged miR-17–3p and miR-181b-5p to induce the expression of TIMP3 in order to inhibit growth and metastasis." (PMID 34992634, 2021).
renal fibrosis (11 papers, 2013 to 2025). A final common manifestation of a wide variety of chronic kidney diseases characterized by glomerulosclerosis and tubulointerstitial fibrosis. "In contrast, some studies found that long-term exposure to arsenic, possibly due to downregulation of TIMP3, and TIMP3 deficiency may lead to oxidative stress, resulting in increased renal fibrosis." (PMID 36767251, 2023). "Overexpression of the lncRNA TUG1 inhibits cell fibrosis in high glucose-stimulated NRK-52E cells and renal fibrosis in DN mice by targeting the miR-21 and promoting the expression of TIMP3." (PMID 35865316, 2022). "The authors suggest that the protective effect of TIMP-3 is due to suppression of TNFα, which mediates renal fibrosis and regulates expression of several MMPs." (PMID 24713275, 2014). "TIMP3 is the most highly expressed TIMP in the kidney and has a broad protease inhibition profile; loss of this protein is associated with age-dependent renal fibrosis and tubulointerstitial injury in mice." (PMID 23401241, 2013). "Renal fibrosis in Timp3-null mice is associated with aberrant ADAM17-mediated shedding of TNF, as TNF ablation rescued tissue thinning and the other lesions displayed by Timp3-null mice." (PMID 35207132, 2022). "Mir-181a-5p has been found to downregulate lipid metabolism regulator PPARα and is in silico predicted to downregulate MAT2A, TIMP3, and LGSF11; miR-451 downregulates YWHAZ and CAB39, which could be implicated in renal fibrosis and mesangial hypertrophy." (PMID 32849923, 2020).
cardiac hypertrophy (10 papers, 2012 to 2023). "Meanwhile, deficiency of TIMP3 has been found capable to suppress Ang II-induced cardiac hypertrophy, but to enhance pressure overload-induced DCM primarily due to increased activity of ADAM17, TNFα and MMPs." (PMID 37057103, 2023). "As we have found that deficiency of TIMP3 reduced angiotensin II (Ang II)-induced cardiac hypertrophy." (PMID 37057103, 2023). "Compared with wild-type (WT) mice, cardiac pressure overload in Timp3-knockout (Timp3–/–) mice leads to more severe LV dilation, systolic and diastolic dysfunction, cardiac hypertrophy and fibrosis, with early heart failure." (PMID 32612540, 2020). "Another study also showed that tRF-5 was abundant in the sperm of mice with myocardial hypertrophy and inhibited the mRNA expression of the hypertrophy regulator TIMP3 by binding its 3′UTR sequence, thereby aggravating cardiomyocyte hypertrophy, increasing cardiac fibrosis and promoting apoptosis." (PMID 36247465, 2022). "We have previously reported the role of anti-angiogenic factors in inducing the transition from compensatory cardiac hypertrophy to heart failure and the significance of MMP-9 and TIMP-3 in promoting this process during pressure overload hemodynamic stress." (PMID 22479323, 2012). "For example, tRFs are involved in isoprenaline myocardial hypertrophy in Sprague-Dawley rats, perhaps specifically because tRF-5 binds to the 3′ UTR of the hypertrophy regulator TIMP3 mRNA and inhibits its expression, which leads to hypertrophy of cardiac myocytes." (PMID 36553526, 2022).
diabetic retinopathy (10 papers, 2016 to 2025). "In an in vivo and in vitro study on diabetic retinopathy, a decrease in TIMP3 expression was accompanied by an increase in oxidative stress injury, which was manifested by an increase in ROS and a decrease in SOD and CAT enzyme activities." (PMID 40893347, 2025). "MiR-221-3p promotes diabetic wound healing by targeting HIPK285 and regulates microvascular dysfunction in diabetic retinopathy by targeting TIMP3." (PMID 38699234, 2024). "Regulation of TIMP3 by miR-221-3p was described in diabetic retinopathy and by miR-221-3p and miR-222-3p chronic liver disease." (PMID 35008952, 2022). "The miR-365/TIMP-3 pathway is a potential therapeutic target for the treatment of diabetic retinopathy." (PMID 33419373, 2020). "miR-365 is highly expressed in the retina, and the dysfunction of the miR-365/TIMP-3 pathway is closely related to diabetic retinopathy." (PMID 33419373, 2020). "miR-122 promoted diabetic retinopathy through targeting TIMP3, making miR-122 a promising target for diabetic retinopathy therapy." (PMID 33209201, 2020). "In a number of studies TIMP-3 has been administered as a therapeutic agent and has shown promise to reduce oxygen-induced retinopathy and reduce inflammatory changes in diabetic retinopathy." (PMID 39544367, 2024). "Similarly, a study showed that hsa-miR-221-3p regulates microvascular dysfunction in diabetic retinopathy by targeting TIMP3." (PMID 34948403, 2021). "Heavily oxidised and glycated LDL have been found to reduce expression of TIMP3 (tissue inhibitor of metalloproteinases 3) which might contribute to microvascular abnormalities in diabetic retinopathy." (PMID 27896233, 2016). "Hence, we concluded that miR-122 promoted diabetic retinopathy through targeting TIMP3, and miR-122 might be a useful treatment target for DR." (PMID 33209201, 2020).
esophageal cancer (10 papers, 2004 to 2024). A primary or metastatic malignant neoplasm involving the esophagus. "The downregulation of TIMP3 by miR-373 also increases the proliferation of oesophagal cancer cells and metastatic ability." (PMID 38542164, 2024). "The expression levels of TIMP3 in oesophagal cancer tissues and plasma from patients are significantly lower than those in normal tissue and plasma from healthy volunteers, respectively." (PMID 38542164, 2024). "Decreasing expression of TIMP-3 in invasive oesophageal cancer cells may indicate that one of the functions of TIMP-3 is suppression of invasiveness." (PMID 15467768, 2004). "We observed a downregulation of TIMP3 and COL4A1 in normal fibroblasts that were juxtaposed to esophageal cancer cells and this downregulation is consistent with the duration of co-culture and with the increase of miR-21 in the system." (PMID 24039846, 2013).
heart failure (10 papers, 2011 to 2026). Inability of the heart to pump blood at an adequate rate to meet tissue metabolic requirements. "It has also been reported that TIMP3 levels are significantly reduced in patients with dilated cardiomyopathy and heart failure, and even the loss of a single TIMP3 allele in mice leads to myocardial fibrosis." (PMID 34141473, 2021). "To evaluate the biological activity of TIMP3 as a heart failure target, we characterized N‐TIMP3 (N‐domain, 13.9 kDa), TIMP3v2 (K22S/F34N), 5xGlyco‐TIMP3 (v82), and v82 with Fc fused in the C‐terminus (v82‐Fc)." (PMID 30459952, 2018). "Interestingly, among these miRNAs, miR-206 was also reported to play important roles via inhibition of TIMP3 in cardiac fibroblasts in heart failure models." (PMID 26683101, 2016). "Indeed, TIMP-3 levels are significantly reduced in patients with dilated cardiomyopathy and heart failure." (PMID 21731608, 2011). "Furthermore, genes for fibrotic regulators, such as TGFβ1, TIMP1, TIMP3, TIMP4, and ADAMTS1, were linked to CLIC expression, reinforcing the hypothesis that CLICs contribute to fibrotic progression and ECM remodeling in human heart failure." (PMID 41521401, 2026). "H2S also provides a clinical possibility for the prevention and treatment of heart failure by upregulating MMP2, downregulating MMP‐9 and TIMP‐3, and promoting angiogenesis through the eNOS‐NO pathway." (PMID 36478328, 2023). "Treatment with H2S donors could inhibit the transition from compensatory hypertrophy to heart failure by inducing the production of MMP‐2, inhibiting the expression of TIMP‐3 and MMP‐9, and promoting the synthesis of VEGF." (PMID 36478328, 2023).
non-small cell lung carcinoma (10 papers, 2012 to 2021). A group of at least three distinct histological types of lung cancer, including non-small cell squamous cell carcinoma, adenocarcinoma, and large cell carcinoma. "TIMP-3 downregulation is associated with aggressive non-small cell lung cancer and hepatocarcinoma cells, as compared with less invasive and/or normal lung and liver cells." (PMID 29236770, 2017). "One study demonstrated that the loss of TIMP3 expression might increase IL-6 production via the tumor necrosis factor α/nuclear factor κB pathway in patients with HPV-infected non-small cell lung cancer." (PMID 29731768, 2018). "miR-221 and miR-222 modulate the resistance to TRAIL and promote tumorigenesis via downregulating PTEN and TIMP3 in both aggressive non-small-cell lung cancer and hepatocarcinomatous cells." (PMID 35145900, 2021). "Another study showed that lysine (K)-specific demethylase 1A (KDM1A) promoted tumor cell invasion by silencing TIMP3 expression in non-small cell lung cancer cells." (PMID 29731768, 2018). "Additionally, recent reports demonstrated that miR-221/222 regulated TRAIL-resistance and enhanced tumorigenicity through PTEN and TIMP3 down-regulation in aggressive non small cell lung cancer and hepatocarcinoma cells." (PMID 26501139, 2015).
Obesity (10 papers, 2014 to 2024). Accumulation of substantial excess body fat. "TIMP-3 function in the development of metabolic disorders associated with obesity was further investigated by crossing the TIMP-3 knockout mouse with the Insr+/− mouse." (PMID 35207132, 2022). "In addition to PS, other factors involved in ADAM17 regulation in obesity should also be considered, as previous research has shown that obesity is characterized by a deficiency of TIMP3 in white adipose tissue and liver, resulting in elevated ADAM17 levels." (PMID 38550672, 2024). "TGF-β expression is positively correlated with the expression of TIMP-1, TIMP-3, and TIMP-4 in adipose tissue of people with obesity." (PMID 37383542, 2023). "In obesity, increased TGF-β signalling has been suggested to exert pro-fibrogenic actions by stimulating the expression of tissue inhibitors of metalloproteases (TIMPs), including TIMP-1, TIMP-3, and TIMP-4, and connective tissue growth factor (CTGF)." (PMID 37383542, 2023).